MPO (myeloperoxidase)
Diseases named in the same sentence as MPO in open-access papers (continued):
Sharing a sentence is not in itself a finding about the gene and the disease.
glomerulonephritis (155 papers, 2006 to 2026). A renal disorder characterized by damage in the glomeruli. "We report a case of severe ITP in a 68-year-old woman on maintenance hemodialysis for 10 years due to myeloperoxidase-anti-neutrophil cytoplasmic antibody (MPO-ANCA)-associated glomerulonephritis, treated with rituximab." (PMID 41939544, 2026). "The most common histological pattern was pauci-immune glomerulonephritis associated with ANCA positivity (n = 3 with a specificity for anti-MPO)." (PMID 41395910, 2025). "Consistent with their findings, FKN was highly expressed in serum and renal tissues in MPO-induced MPO-AAV-associated glomerulonephritis rats." (PMID 38937701, 2024). "C3 represents the most common complement component found in MPO-ANCA-associated glomerulonephritis [60,]." (PMID 38445024, 2024). "MN is sometimes observed along with myeloperoxidase (MPO)-anti-neutrophil cytoplasmic antibody (ANCA)-associated glomerulonephritis; however, some consider MN and ANCA-associated glomerulonephritis to be two mutually independent diseases." (PMID 38892120, 2024). "In this study, we showed differential analysis and localization of chemokine FKN protein levels in a rat model of MPO-AAV-associated glomerulonephritis induced by MPO + Freund’s complete adjuvant." (PMID 38937701, 2024). "MPO-AAV associated glomerulonephritis model was established by intraperitoneal injection of MPO + Freund’s complete adjuvant with 10 mice in each group." (PMID 38937701, 2024). "As a C5aR antagonist, avacopan prevented the development of glomerulonephritis induced by anti-myeloperoxidase antibodies in a murine model of ANCA-associated vasculitis." (PMID 37036661, 2023). "In necrotic glomerulonephritis, IL-17A deficiency leads to impaired neutrophil recruitment to the glomerulus, which, in turn, downregulates MPO and improves glomerulonephritis." (PMID 37920459, 2023). "Compared with AAV-associated typical glomerulonephritis, these cases showed significantly fewer urinary RBCs and tended to exhibit lower levels of sCr, 24hUP, and MPO tilter." (PMID 35759125, 2022). "Our previous study found that low hemoglobin level was connected to a greater KFRT risk in patients with MPO-ANCA associated glomerulonephritis." (PMID 36408940, 2022). "Here, we assess the presence of glomerular immune deposits alongside renal outcome in myeloperoxidase (MPO)-ANCA associated glomerulonephritis (MPO-ANCA GN)." (PMID 33841408, 2021). "Prior reports had shown that there were remarkably higher suPAR levels in 13 patients with MPO-ANCA-associated glomerulonephritis compared with healthy controls, as well as significantly higher suPAR levels in 5 ANCA-GN patients than in non-ANCA-GN patients." (PMID 32322165, 2020). "Antineutrophil cytoplasmic antibodies (ANCA) against proteinase 3 (PR3) and/or myeloperoxidase (MPO) together with glomerulonephritis have been associated with various disorders." (PMID 32005179, 2020). "MPO release in the presence of NETs also was found in kidney biopsies of MPO–ANCA-associated glomerulonephritis patients." (PMID 32276504, 2020). "6PGD391–410 is part of a protein that is immunogenic in humans, can induce loss of tolerance to MPO and experimental anti-MPO glomerulonephritis and MPO-AAV." (PMID 31358739, 2019). "Complement factor C5a receptor deficiency ameliorates MPO-ANCA-induced experimental glomerulonephritis in mice." (PMID 28620373, 2017). "Anti‐MPO antibodies raised in MPO‐deficient mice were shown to cause a focal necrotizing crescentic glomerulonephritis when injected into wild‐type mice." (PMID 27235854, 2016). "The patient had been prescribed with calcium polystyrene sulfonate (CPS) for the treatment of hyperkalemia following myeloperoxidase-antineutrophil cytoplasmic antibody (MPO-ANCA) associated glomerulonephritis." (PMID 24391670, 2013).
glomerulonephritis (continued). "Considering this case retrospectively, our patient had GPA rather than microscopic polyangiitis; the GPA also accounted for her medical history of reversible hearing loss, although her glomerulonephritis remitted with an undetectable level of MPO-ANCA." (PMID 23617946, 2013). "The patient was treated with hemodialysis for myeloperoxidase-antineutrophil cytoplasmic antibody (MPO-ANCA) associated glomerulonephritis and had been receiving CPS (ARGAMATE) for the treatment of hyperkalemia." (PMID 24391670, 2013). "MPO activation is necessary for the formation of NETs and circulating antibodies to MPO were associated with glomerulonephritis and systemic vasculitis." (PMID 23110185, 2012). "Several authors have reported myeloperoxidase antineutrophil cytoplasmic antibody- (MPO-ANCA-) associated glomerulonephritis resulting in renal failure in scleroderma." (PMID 20827302, 2010). "These include scleroderma overlap syndromes with associated features of lupus nephritis, myeloperoxidase anti-neutrophil cytoplasmic antibodies (ANCA) or proteinase 3 ANCA-associated glomerulonephritis, or crescentic glomerulonephritis." (PMID 18474117, 2008). "Interestingly, the renal function and tissue damage in MPO-AAV-associated glomerulonephritis rat model were significantly restored by blocking the action of FKN." (PMID 38937701, 2024). "Taken together, FKN may affect the level of kidney injury in MPO-AAV-associated glomerulonephritis rats by modulating inflammatory signalling pathways." (PMID 38937701, 2024). "However, the involvement of FKN in the pathogenesis of MPO-AAV associated glomerulonephritis and its role in the progression of the disease need to be further studied." (PMID 38937701, 2024). "Thus early withdrawal of immunosuppression should be considered in patients with ESRD due to ANCA-associated glomerulonephritis, especially those with MPO-ANCA." (PMID 33916214, 2021). "Interestingly, passive transfer of purified MPO-ANCA or splenocytes from MPO-deficient mice immunized with purified MPO into wild type mice induced necrotizing pauci-immune glomerulonephritis." (PMID 34205404, 2021). "Autoreactivity to myeloperoxidase (MPO) causes autoimmune vasculitis and severe glomerulonephritis." (PMID 31358739, 2019). "In addition, IgG1 and IgG2 have been reported to be positive in MPO-ANCA-associated glomerulonephritis and MN-lesions." (PMID 29792176, 2018). "The role of IL- 17A has been examined using IL-17A-deficient mice in anti-MPO glomerulonephritis." (PMID 25964886, 2015). "The relationship between these two etiologically distinct entities, MPO-/PR3-negative ANCA-associated glomerulonephritis and MGN, remains unclear." (PMID 25648906, 2015). "Interestingly, recent studies, including the mouse model of anti-MPO IgG mediated glomerulonephritis and human ANCA associated vasculitis, suggested that complement alternative pathway activation was crucial for ANCA associated vasculitis development." (PMID 24672300, 2014). "Overall, this case demonstrates clinicopathologic features consistent with hydralazine-induced pauci-immune ANCA positive glomerulonephritis and provides the first evidence that MPO as well as PR3 ANCAs may be associated with this disease." (PMID 25210633, 2014). "FKN may play a key role in the pathogenesis of MPO-AAV associated glomerulonephritis." (PMID 38937701, 2024). "In contrast, no properdin was found in kidney biopsies of a small cohort of patients with AAV using mass spectrometry, which may be in line with animal studies where properdin was shown to be dispensable for the induction of MPO-ANCA-associated glomerulonephritis." (PMID 34204207, 2021). "On admission, MPA was suspected based on rapidly progressive glomerulonephritis, mononeuritis multiplex, and myeloperoxidase (MPO)-ANCA positivity." (PMID 42317892, 2026).
glomerulonephritis (continued). "Herein, we report the case of a 28-year-old female patient who developed end-stage kidney disease due to rapidly progressive glomerulonephritis with MPO-ANCA and anti-GBM double positivity." (PMID 41209892, 2025). "This study investigates the therapeutic potential of blocking key CD4+ Th1 effector cytokines, TNF-α and IFN-γ, in experimental anti-myeloperoxidase (MPO) glomerulonephritis (GN)." (PMID 40735321, 2025). "Collectively, the data from 2 different and complementary models of anti-MPO GN indicate that ecDNA deposition can be cleared by exogenous DNase I, resulting in significantly attenuated glomerulonephritis." (PMID 40632882, 2025). "MPO-ANCA has been shown to stimulate IL-17 production, driving autoimmune anti-myeloperoxidase glomerulonephritis." (PMID 41181091, 2025). "Higher rates of glomerulonephritis are reported in MPO-AAV patients, with over 80% experiencing kidney disease at initial presentation, often progressing to chronic kidney injury and adversely affecting survival." (PMID 40095487, 2025). "The presence of PR3 or MPO-ANCA is highly predictive of pauci-immune glomerulonephritis in an appropriate clinical presentation, warranting early treatment for patients who present with organ- or life-threatening disease." (PMID 39927255, 2025). "ANCA-positive EGPA (usually MPO-ANCA) follows a vasculitic course characterized by small-vessel inflammation leading to glomerulonephritis, mononeuritis multiplex, alveolar hemorrhage, and purpura." (PMID 41303621, 2025). "ANCA testing, particularly for myeloperoxidase-ANCA (MPO-ANCA), has a sensitivity of approximately 40% in EGPA patients, and is associated with more vasculitic features such as glomerulonephritis, neuropathy, and skin manifestations." (PMID 40534692, 2025). "Several chemokines were found to be upregulated during anti-MPO IgG-induced glomerulonephritis, and interestingly, they found that renal (mainly glomerular) cells and infiltrating inflammatory cells were in part responsible for the production of chemokines." (PMID 38937701, 2024). "Pretreatment with a C5-inhibiting monoclonal antibody in a mouse model of anti-myeloperoxidase IgG-induced glomerulonephritis significantly reduced glomerular crescent formation." (PMID 38590952, 2024). "Eight patients presented with ILD on chest imaging, and one of them had histopathological features of pauci-immune glomerulonephritis, on biopsy in addition to MPO-ANCA (or P-ANCA) positivity and pulmonary features." (PMID 37959218, 2023). "This study investigates dendritic cell TLR9 ligation in murine experimental anti-MPO glomerulonephritis." (PMID 36674855, 2023). "It was found that patients with SLE and glomerulonephritis had significantly higher serum MPO-DNA complex levels." (PMID 37298160, 2023). "MPO-AAV usually involves the glomeruli causing membranous changes and presents with glomerulonephritis." (PMID 38234965, 2023). "Fostamatinib is a highly selective Syk inhibitor, and it was proven to improve MPO-ANCA glomerulonephritis in a pre-clinical ANCA vasculitis model in Wistar Kyoto rats." (PMID 37744367, 2023). "Selective PADI-4 inhibitor, GSK484 was successful in anti-MPO glomerulonephritis by reducing the inflammatory response and the subsequent segmental necrosis." (PMID 35721093, 2022). "In particular, a central role of C5aR1 has been identified in these models supported by findings in other autoimmune disorders such as anti-myeloperoxidase glomerulonephritis, autoimmune uveitis, and psoriasis." (PMID 36466856, 2022). "On the other hand, in C5aR-deficient mice, glomerulonephritis induced by MPO-ANCA passive transfer is completely suppressed, indicating that cAP-mediated C5a and its receptor C5aR are essential for the pathogenesis of glomerulonephritis in the AAV mouse model." (PMID 35812453, 2022).
glomerulonephritis (continued). "In experimental anti-MPO glomerulonephritis, genetic or pharmacologic C5aR1 targeting resulted in attenuated TH1 immunity and increased frequency of regulatory T cells (Tregs) eventually mitigating autoimmunity to MPO." (PMID 35958588, 2022). "Similar cases were seen with influenza vaccination, potentially describing vaccination as a possible trigger for anti-myeloperoxidase rapidly progressive glomerulonephritis." (PMID 36348922, 2022). "In fact, autoantibodies directed against LAMP-2 (anti-LAMP-2) are frequently detected in both MPO and PR3-ANCA-associated glomerulonephritis, as well as in ANCA(−) glomerulonephritis." (PMID 36294902, 2022). "In accordance with these findings, targeting cytokines associated with the differentiation of CD4+ T helper cell subsets was effective in improving anti-MPO glomerulonephritis." (PMID 34289887, 2021). "In murine anti-MPO glomerulonephritis, Th17 and Th1 cells were demonstrated to promote the development of autoimmune renal damage." (PMID 34289887, 2021). "Often, the effect of the granule contents on T‐cell responses are context‐dependent; MPO induces pro‐inflammatory T‐cell responses in patients with anti‐MPO glomerulonephritis due to its role as an autoantigen." (PMID 34287859, 2021). "Blood testing revealed elevated titers of myeloperoxidase anti-neutrophil cytoplasmic antibodies, and renal biopsy revealed crescentic glomerulonephritis with broad hyalinization of most of the glomeruli and a pauci-immune staining pattern." (PMID 34126959, 2021). "In patients with anti-MPO glomerulonephritis, MPO-specific CD4+ T cells mediate organ damage, recognizing MPO released by NETosis as an autoantigen, conducting delayed-type hypersensitivity promoting IFN-γ and IL-17A production." (PMID 33176801, 2020). "Autoreactivity to myeloperoxidase (MPO) causes anti-neutrophil cytoplasmic antibody (ANCA)-associated vasculitis (AAV), with rapidly progressive glomerulonephritis." (PMID 31358739, 2019). "Using this protocol, mice immunized with the S. aureus JH1-derived pSJH101 6PGD391–410 peptide developed glomerulonephritis of similar severity to MPO-immunized mice with elevated albuminuria, glomerular segmental necrosis, and inflammatory cell infiltrates." (PMID 31358739, 2019). "Mice immunized with 6PGD391–410, or with S. aureus containing a plasmid expressing 6PGD391–410, develop glomerulonephritis when MPO is deposited in glomeruli." (PMID 31358739, 2019). "MPO-immunized mice develop glomerulonephritis with pathological albuminuria and segmental glomerular necrosis." (PMID 31358739, 2019). "Using two different murine models of anti-myeloperoxidase (MPO) glomerulonephritis, one mediated by passive transfer of anti-MPO antibodies, the other by cell-mediated immunity, we found that the C3aR did not alter histological disease severity." (PMID 29315316, 2018). "Having excluded this potential confounder, we induced autoimmune anti-MPO glomerulonephritis in WT and C3ar-/- mice." (PMID 29315316, 2018). "Depletion studies have implicated macrophages as important injurious mediators in murine models of glomerulonephritis including disease induced by anti-MPO IgG." (PMID 29315316, 2018). "We therefore examined the role of signalling through the C3aR in anti-MPO autoimmunity and renal injury, by studying C3ar-/- mice in two complementary models of anti-MPO glomerulonephritis." (PMID 29315316, 2018). "We then examined the role of C3aR in an autoimmune model of anti-MPO glomerulonephritis that is mediated by the T cell effector response to glomerular MPO." (PMID 29315316, 2018). "We used this enhanced model to investigate the role of the endogenous C3a in the effector phase of anti-MPO IgG induced glomerulonephritis." (PMID 29315316, 2018). "The model of autoimmune anti-MPO glomerulonephritis relies on immunisation with MPO in Freund’s complete adjuvant to break immune tolerance and generate autoimmunity." (PMID 29315316, 2018).
glomerulonephritis (continued). "Glomerular MPO is recognised by antigen specific effector T cells with resulting necrotising glomerulonephritis." (PMID 29315316, 2018). "Passive transfer of anti-MPO IgG into mice induces a neutrophil mediated necrotising glomerulonephritis." (PMID 29315316, 2018). "We report two patients diagnosed with anti-neutrophil cytoplasmic antibody (ANCA)-associated glomerulonephritis with MN-lesions, in whom ANCA titers for myeloperoxidase (MPO) were persistently positive." (PMID 29792176, 2018). "In this murine anti‐MPO model, both the histological and the clinical features of glomerulonephritis closely mirror the situation in patients." (PMID 27235854, 2016). "The production of IL-1β has been shown to play a critical role in the pathogenesis of ANCA vasculitis, with the IL-1 receptor antagonist anakinra protecting against glomerulonephritis in an anti-MPO-induced mouse model." (PMID 26149790, 2015). "This is a rare case of rapidly progressive glomerulonephritis due to dual MPO-ANCA antibodies and anti-GBM antibodies (DAV)." (PMID 26301224, 2015). "Meanwhile, CS has distinct features related to atopy and eosinophilia despite shared features of pauci-immune glomerulonephritis and positive MPO-ANCA." (PMID 24884372, 2014). "Our patient presented with an unusual clinical course: complete hearing loss followed by glomerulonephritis accompanied by an elevated serum titer of myeloperoxidase (MPO)-ANCA and subsequent visual loss with an undetectable level of MPO-ANCA." (PMID 23617946, 2013). "However, pDCs from MPO-ANCA patients with rapidly progressive glomerulonephritis exhibited a reduced ability to produce IFN-α upon stimulation." (PMID 40649843, 2025). "Hydralazine-modified MPO induces glomerulonephritis in anti-MPO splenocyte-recipient mice." (PMID 40020049, 2025). "Various presentations of kidney pathology in SSc are hypertensive SRC, normotensive SRC, isolated reduced glomerular filtration rate, myeloperoxidase anti‐neutrophil cytoplasmic antibody‐glomerulonephritis (MPO‐ANCA GN), reduced renal function reserve and disparate renal vascular resistance indices." (PMID 38660003, 2024). "In patients with MPO-AAV and glomerulonephritis, it has been recently described that persistence or subsequent reappearance of MPO-ANCA is associated with a higher risk of relapse, while MPO-ANCA negativity stratifies a low risk for relapse even without remission maintenance therapy." (PMID 38445024, 2024). "Patients with SLE and glomerulonephritis had significantly higher levels of the MPO-DNA complex." (PMID 37298160, 2023). "Initially, the patient developed thrombocytopenia without any abnormalities of liver function; however, a positive myeloperoxidase antineutrophil cytoplasmic antibody (ANCA) test and the presence of alveolar hemorrhage and glomerulonephritis confirmed ANCA-associated vasculitis." (PMID 37303320, 2023). "Therefore, this study was undertaken to assess this in a preclinical model of glomerulonephritis induced by the transfer of antibodies to MPO." (PMID 35818684, 2023). "This last patient, indeed, both responded to HUV classification criteria (chronic urticaria, complement consumption, arthralgia, glomerulonephritis, and anti-C1q antibodies) and displayed features of AAV (arthralgia, glomerulonephritis and anti-MPO antibodies)." (PMID 35172758, 2022). "Bortezomib proved to be efficient in a mouse model of MPO-ANCA glomerulonephritis." (PMID 35721093, 2022). "However, studies in a mouse model of MPO‐ANCA‐induced glomerulonephritis sought to elucidate the relationship between anti‐CD20‐induced B‐cell depletion and T cells." (PMID 36381498, 2022). "Significantly, a study on experimental murine anti-MPO glomerulonephritis model found that the renal involvement of T helper subset is biphasic, the dominance of the Th17 subset during the development of early autoimmunity followed by Th1 dominance in late autoimmunity." (PMID 34289887, 2021).